HSPG2 (heparan sulfate proteoglycan 2)
Diseases named in the same sentence as HSPG2 in open-access papers (continued):
Sharing a sentence is not in itself a finding about the gene and the disease.
colon carcinoma (3 papers, 2019 to 2023). "Downregulation of HSPG2 expression using antisense in colon carcinoma cells resulted in decreased tumor growth and angiogenesis." (PMID 31462656, 2019). "Moreover, HSPG2 had higher expression in the colon cancer-initiating cell line AG2 compared to HCT116 carcinoma cells." (PMID 37241967, 2023).
fatty liver disease (3 papers, 2021 to 2025). A reversible condition wherein large vacuoles of triglyceride fat accumulate in liver cells via the process of steatosis. "We identified 78 secreted proteins that were positively associated with liver steatosis area, with the top hits including fatty acid binding protein 4 (FABP4), kallistatin (SERPINA4), perlecan (HSPG2); all have known roles in lipid metabolism and driving MASLD progression." (PMID 40250425, 2025).
glioblastoma (3 papers, 2019 to 2025). The most malignant astrocytic tumor (WHO grade IV). "Similarly, Perlecan/HSPG2 is markedly upregulated in glioblastoma, exhibiting a 13–14 fold increase." (PMID 40076738, 2025). "Similarly, in glioblastoma, high HSPG2 expression in the tumor correlated with poor relapse-free survival." (PMID 31462656, 2019).
idiopathic scoliosis (3 papers, 2014 to 2019). A scoliosis with no known cause. "Based on these results, we conclude that rare variants in the HSPG2 gene potentially contribute to the idiopathic scoliosis phenotype in a subset of patients with idiopathic scoliosis." (PMID 25504735, 2014). "Exome sequencing was completed for three members of this multigenerational family with idiopathic scoliosis, resulting in the identification of a variant in the HSPG2 gene as a potential contributor to the phenotype." (PMID 25504735, 2014). "Besides these two Mendelian inherited conditions, a missense mutation in HSPG2 (p.Asn786Ser) has recently been linked with idiopathic scoliosis based on exome sequencing analysis of a multigenerational family of European ancestry with familial scoliosis." (PMID 28327142, 2017). "Furthermore, we identified additional rare HSPG2 variants that are predicted to be damaging in two independent cohorts of individuals with idiopathic scoliosis." (PMID 25504735, 2014). "The HSPG2 gene was sequenced in a separate cohort of 100 unrelated individuals affected with idiopathic scoliosis and also was examined in an independent idiopathic scoliosis population." (PMID 25504735, 2014). "Further studies must be completed to confirm the effect of the HSPG2 gene on the idiopathic scoliosis phenotype." (PMID 25504735, 2014).
Marfan syndrome (3 papers, 2020 to 2024). A disorder of the connective tissue. "A recent study suggested that HSPG2, encoding perlecan, is a modifier gene for Marfan syndrome." (PMID 35008739, 2021).
melanoma (3 papers, 2019 to 2025). A malignant, usually aggressive tumor composed of atypical, neoplastic melanocytes. "Herein, we aim to investigate the immunotherapeutic and immunological roles of HSPG2 mutations in melanoma and NSCLC." (PMID 35884556, 2022). "The findings derived from this work show that HSPG2 mutations were connected with an improved outcome in melanoma and NSCLC patients under an immunotherapy setting." (PMID 35884556, 2022). "A melanoma univariate prognosis analysis revealed that patients with HSPG2 mutations presented a significantly more prolonged outcome than HSPG2 wild-type patients (median survival time: 49.3 vs. 25.7 months, Log–rank test p = 0.012)." (PMID 35884556, 2022). "We thus investigated the correlation between HSPG2 mutations and melanoma TMB." (PMID 35884556, 2022). "Heparan sulfate proteoglycan 2 (HSPG2) is frequently mutated in melanoma and NSCLC." (PMID 35884556, 2022). "In melanoma, we performed analyses of immune infiltration, immunogenicity signatures, and pathway enrichment to elucidate the potential immunological mechanisms of HSPG2 mutations." (PMID 35884556, 2022). "Melanoma patients with HSPG2 mutations had a markedly extended ICI outcome than other patients." (PMID 35884556, 2022). "Collectively, based on the aggregated melanoma and NSCLC immunotherapeutic cohorts, we discovered that HSPG2 mutations were associated with better tumor immunogenicity and ICI treatment efficacy." (PMID 35884556, 2022). "We also used the mutational profiles of melanoma samples from the TCGA cohort and observed a significantly elevated TMB and NB in HSPG2-mutated patients (Wilcoxon rank sum test both p < 0.001)." (PMID 35884556, 2022). "In this study, based on the integrated ICI-treated 631 melanoma and 109 NSCLC samples, we observed that HSPG2 mutations were predictive of a favorable ICI treatment outcome, which provides evidence for customizing immunotherapeutic strategies." (PMID 35884556, 2022). "In this study, HSPG2 mutations were also determined to link with an elevated mutational burden and a preferable ICI efficacy in melanoma and NSCLC, which indicates that HSPG2 mutations may be a possible indicator for TMB and cancer immune treatment response." (PMID 35884556, 2022). "Finally, based on 631 melanoma and 109 NSCLC samples, we investigated the immunological and clinical immunotherapeutic implications of HSPG2 alterations." (PMID 35884556, 2022).
preeclampsia (3 papers, 2022 to 2023). Preeclampsia is a hypertensive disorder of pregnancy that is characterized by new-onset hypertension with proteinuria presenting after 20 weeks of gestation, and depending on mild or severe forms may initially present with severe headache, visual disturbances, and hyperreflexia. "Although this study had a different design, and it was found that the HSPG2 level increased in the severe preeclampsia group in proportion to systolic and diastolic blood pressure, liver and kidney function tests, the authors did not link these effects with eGC damage." (PMID 36359309, 2022). "Pseudo-time analysis of the EVT1 and EVT2 subtypes suggested that CSH1 and HSPG2 may regulate EVT differentiation, and both are downregulated in preeclamptic EVT, in line with previous placenta transcriptomics of women with both early-onset and late-onset preeclampsia." (PMID 37854606, 2023).
aneurysm (2 papers, 2019 to 2020). Bulging or ballooning in an area of an artery secondary to arterial wall weakening. "Moreover, we showed that lower expression of Hspg2 is associated with more severe hyperkyphosis, and with lower integrity of elastic fibers and presence of aneurysms." (PMID 32514132, 2020). "Similarly, expression of Hspg2 in aorta was lower in the severely affected and the aneurysm group when compared with mildly affected animals (p < 0.05)." (PMID 32514132, 2020).
asthma (2 papers, 2024 to 2025). "In addition, our group has previously shown changes associated with asthma in the serum levels of many of the proteins detected in urine, i.e., IGFALS, FCN2, HSPG2, CD26/DPP4, and CD14, and suggested their use as potential phenotype/severity biomarkers of this disease." (PMID 39858454, 2025).
Balkan endemic nephropathy (2 papers, 2014 to 2024). "Besides, variants in the HSPG2 gene have also been associated with various skeletal and renal disorders, including scoliosis, diabetic nephropathy (DN), Balkan endemic nephropathy (BEN), and KSD." (PMID 39680213, 2024).
heart failure (2 papers, 2022 to 2025). Inability of the heart to pump blood at an adequate rate to meet tissue metabolic requirements. "Upregulation of HSPG2 has been reported in DCM patients, and increased expression in these patients has been strongly associated with immune activation, cardiac fibrosis and heart failure." (PMID 39982482, 2025).
hepatitis B (2 papers, 2021 to 2025). "For those of normal weight, the hepatitis B pathway, composed of RB1, EP300, PIK3CB, HSPG2 and JAK1 (K = 9), may serve as a key point for effective treatment and prevention, because chronic infection with hepatitis viruses is a major causative factor for hepatocellular carcinoma." (PMID 40768543, 2025).
leukaemia (2 papers, 2020 to 2025). "Moreover, long‐term effects of HSPG2 on both normal haematopoiesis and leukaemia recurrence risk need to be further elucidated by long‐term monitoring in AML patients after chemotherapy." (PMID 39914998, 2025). "Patients with high HSPG2 expression had both worse overall survival (OS) (P = 0.001) and poorer leukemia-free survival (LFS) (P = 0.047)." (PMID 32606327, 2020). "This study aims to investigate the prognostic value of the HSPG2 gene in terms of overall survival and leukemia-free survival in patients with AML." (PMID 32606327, 2020). "In summary, this work demonstrated that HSPG2 can repair the BM EPC function in AML‐CR patients after chemotherapy without altering their leukaemia cell‐supporting ability." (PMID 39914998, 2025). "In addition, we found that the HSPG2 treatment restored the BM EPC function from CR patients without affecting their leukaemia cell‐supporting ability." (PMID 39914998, 2025). "Importantly, we found that HSPG2 did not increase the leukaemia cells‐supporting ability of CR EPC." (PMID 39914998, 2025). "Importantly, the HSPG2 treatment did not increase the leukaemia cell‐supporting ability of CR EPCs, which specifically manifested as no significant increase in cell proliferation ability, no significant decrease in cell apoptosis and no significant changes in the CFU‐L formation ability." (PMID 39914998, 2025). "We subsequently investigated whether HSPG2 can restore the BM EPC function of CR patients, especially their haematopoiesis‐supporting ability, without affecting their leukaemia cell‐supporting ability." (PMID 39914998, 2025).
lung adenocarcinoma (2 papers, 2022 to 2024). A carcinoma that arises from the lung and is characterized by the presence of malignant glandular epithelial cells. "We found that TGFB1, ENG, TGM2, TBXA2R, HSPG2, and PTPRS were significantly upregulated in lung adenocarcinoma cells." (PMID 36249427, 2022).
metastatic carcinoma (2 papers, 2022 to 2023). A carcinoma which has spread from the original site of growth to another anatomic site. "Heparan sulfate proteoglycan 2 (HSPG2) or perlecan, whose pro-metastasis function was identified, was observed more expression in metastatic CAFs than in weakly metastatic cancer." (PMID 37784082, 2023). "Among these, heparan sulfate proteoglycan 2 (HSPG2), also known as perlecan, is massively deposited in the TME of invasive and metastatic carcinomas and various tumors, more generally all those undergoing epithelial–mesenchymal transition (EMT)." (PMID 35887248, 2022).
oligoastrocytoma (2 papers, 2020 to 2022). A WHO grade II tumor composed of a conspicuous mixture of two distinct neoplastic cell types morphologically resembling the tumor cells in oligodendroglioma and diffuse astrocytoma. "Besides, it is reported that the overexpression of HSPG2 predicts poor survival in patients with oligoastrocytoma and oligodendroglioma." (PMID 32606327, 2020). "As reported in oligoastrocytoma and oligodendroglioma, high expression of HSPG2 could independently predict poor OS and RFS13." (PMID 32606327, 2020).
schizophrenia (2 papers, 2018 to 2021). A major psychotic disorder characterized by abnormalities in the perception or expression of reality. "Association between TD and HSPG2 rs2445142 was observed in an independent GWAS that studied a cohort of 100 Japanese schizophrenia patients that included 50 patients with TD." (PMID 35140610, 2021). "The Perlecan (HSPG2) gene was found to be significantly associated with TD in Japanese schizophrenia patients, and this association was subsequently replicated by an independent research group." (PMID 30283332, 2018). "The GWAS included 100 Japanese schizophrenia patients (50 with treatment-resistant TD) and the findings were validated in an independent cohort of 172 patients (36 with treatment-resistant TD), identifying an association between several polymorphisms in the HSPG2 gene and TD." (PMID 35140610, 2021). "The HSPG2 association was replicated in a refined sample from the CATIE trial, consisting of 179 schizophrenia patients of European ethnicity, as well as a sample of Jewish Israeli schizophrenia patients." (PMID 30283332, 2018). "The HSPG2 rs2445142 G allele was found to be the risk allele for TD in a GWAS on 86 Japanese schizophrenia patients with treatment-resistant TD and 186 without." (PMID 30283332, 2018).
short-limbed dwarfism (2 papers, 2020 to 2025). "In humans, complete loss of perlecan/HSPG2 leads to Dyssegmental Dysplasias Silverman-Handmaker (DDSH) syndrome (OMIM#224410), a lethal form of neonatal short-limbed dwarfism." (PMID 32013135, 2020).
adolescent idiopathic scoliosis (1 paper, 2019). A scoliosis with no known cause arising in adolescent. "Rare variants of HSPG2 have recently been reported to function as a potential contributor to the susceptibility of adolescent idiopathic scoliosis (AIS) in the Caucasians." (PMID 30646882, 2019).
Aortic dissection (1 paper, 2024). Aortic dissection refers to a tear in the intimal layer of the aorta causing a separation between the intima and the medial layers of the aorta. "While perlecan-null mice succumb perinatally, perlecan deficiency significantly increases the incidence of aortic dissection in a lethality-rescued transgenic model (Hspg2 −/−–Tg)." (PMID 38545339, 2024).
bacteremia (1 paper, 2025). "Children with unexplained fever and high CRP had a gene expression profile distinct from those with bacteremia, including downregulated CXCL1, MYOZ3, and HSPG2." (PMID 40806258, 2025).
bladder cancer (1 paper, 2023). "In this study, we established the GMII consisting of eight glutamine metabolism-related genes (ENPP1, GALK1, TALDO1, CYP19A1, FASN, AHCY, SLC7A9, and HSPG2), a high value of which is associated with poor prognosis in bladder cancer patients." (PMID 36911676, 2023). "The expression of five of the eight GMII genes (TALDO1, AHCY, FASN, GALK1 and SLC7A9) in bladder cancer tissues was higher than that in normal tissues, while ENPP1, CYP19A1 and HSPG2 were down-regulated in tumor tissues (p < 0.05)." (PMID 36911676, 2023).
colorectal tumor (1 paper, 2022). "Furthermore, in a TAM-deficient colorectal tumor model, several ECM-related proteins, including HSPG2, were downregulated, suggesting the contribution of TAMs in HSPG2 deposition." (PMID 35887248, 2022).
COVID-19 (1 paper, 2023). A disease caused by infection with severe acute respiratory syndrome coronavirus 2. "The most changed components of BM included laminins (LAMB2, LAMA2, LAMC3, LAMB1, LAMC1, and LAMA5) and proteoglycans (COL18A1, HSPG2, and AGRN), with some BM specific collagens (IV, VIII, XVIII, and V collagens) remaining in COVID-19 brains, as compared with the control brains." (PMID 36609561, 2023).
dyssegmental dysplasia, Rolland-Desbuquois type (1 paper, 2018). "While Dyssegmental dysplasia Rolland Desbuquois type is considered the milder spectrum of DD, it is unclear at this time if this condition is related to HSPG2, as mutations in HSPG2 have not been reported so far in DDRD patients." (PMID 29526034, 2018).
emphysema (1 paper, 2023). "KEGG pathway analysis showed upregulation of the term “ECM-receptor interaction”, which includes integrin subunit alpha 3 (ITGA3), collagen type VI α1 chain (COL6A1), and heparan sulfate proteoglycan 2 (HSPG2) in the non-emphysema subgroup." (PMID 38203236, 2023).
fibrosis (1 paper, 2018). the formation of excess fibrous connective tissue in an organ or tissue in a reparative or reactive process. "HSPG2 has been implicated in several fibrotic processes, including liver fibrosis and desmoplastic tumors." (PMID 30327649, 2018).
Hip dysplasia (1 paper, 2017). The presence of developmental dysplasia of the hip. "HSPG2 variation has been linked to hip dysplasia in both human and mice." (PMID 28327142, 2017). "Only 2 genes (HSPG2 and ATP2B4) were found to be linked to hip dysplasia or other skeletal or bone/joint abnormalities." (PMID 28327142, 2017).
hyperkyphosis (1 paper, 2020). "In contrast, mice with severe hyperkyphosis had lower expression of Hspg2 in comparison with the mild group (p < 0.05)." (PMID 32514132, 2020).
IgA nephropathy (1 paper, 2023). "For example, IgA nephropathy (IgAN), which is one of the most prevalent chronic glomerular diseases, had significantly more matrisome proteins (Col4a1, Lamb1, Hspg2, Emilin, Fgg and Fbln) in diseased patients compared to healthy patients." (PMID 36769148, 2023).
intracranial aneurysms (1 paper, 2019). "We aimed to investigate whether the polymorphisms of gene heparan sulfate proteoglycan 2 (HSPG2) and chondroitin sulfate proteoglycan 2 (CSPG2) are associated with increased risk of intracranial aneurysms (IAs) susceptibility." (PMID 31970092, 2019).
Kyphoscoliosis (1 paper, 2014). An abnormal curvature of the spine in both a coronal (lateral) and sagittal (back-to-front) plane. "This is similar to the Hspg2 homozygous knockout mouse, which exhibits significant kyphoscoliosis and skeletal defects." (PMID 25504735, 2014).
liver fibrosis (1 paper, 2023). "HSPG2 is a main component of the blood vessel basement membrane and is implicated in a variety of fibrotic diseases, including liver fibrosis." (PMID 37443817, 2023).
low grade glioma (1 paper, 2025). A grade I or grade II glioma arising from the central nervous system. "Other relevant pathways in cancer, such as focal adhesion, cytoskeleton regulation, and chemokine signalling (VCL, THBS1-4, FLNA, LAMA2/4/5, HSPG2), might also be influenced indirectly by changes in the WWOX/HIF1A ratio, potentially impacting the overall prognosis of low-grade glioma patients." (PMID 41007296, 2025).
lysosomal storage disorders (1 paper, 2021). "ERT treatment improves HSPG2 levels, recently associated with lysosomal storage disorders and involved in the regulation of autophagy mediated by mTOR signaling." (PMID 33799647, 2021).
multiple sclerosis (1 paper, 2020). A progressive autoimmune disorder affecting the central nervous system resulting in demyelination. "HSPG2 that we found to be upregulated in inactive and remyelinating multiple sclerosis lesions is one of the largest extracellular matrix molecules." (PMID 32272486, 2020).
myeloid leukemia (1 paper, 2020). A clonal proliferation of myeloid cells and their precursors in the bone marrow, peripheral blood, and spleen. "As shown in the results of RT-qPCR, the expression of HSPG2 was significantly upregulated in AML patients (P < 0.001), and human myeloid leukemia cell lines (SKM-1 cells and K562 cells) (P < 0.001), but not in human T cell acute lymphoblastic leukemia cell line (Jurkat cells) (P > 0.05)." (PMID 32606327, 2020).
myopia (1 paper, 2018). "Among these ocular disease related or direct high myopia related genes, five genes (CSMD1, HSPG2, RPGR, SEMA4A and USH2A) have pathogenic variants in multiple patients." (PMID 30245926, 2018). "In addition to the novel mutations found in five known myopia genes (ADAMTS18, CSMD1, P3H2, RPGR, and SLC39A5), we also identified pathogenic variants in seven ocular disease genes (ABCA4, CEP290, HSPG2, PCDH15, SAG, SEMA4A, and USH2A) as novel candidate genes." (PMID 30245926, 2018).
pancreatic adenocarcinoma (1 paper, 2019). "In pancreatic adenocarcinoma, progressive loss of stromal HSPG2 expression was shown to correlate with disease progression." (PMID 31462656, 2019).
pancreatitis (1 paper, 2021). Inflammation of the pancreas. "We performed peptide level analysis to survey BMP1’s other targets and found that HSPG2 LG3 domain is partially but significantly retained in diseased tissues (PanIN, pancreatitis, and PDAC) as compared to normal pancreas." (PMID 33879793, 2021).